TNF (tumor necrosis factor)
Diseases named in the same sentence as TNF in open-access papers (continued):
Sharing a sentence is not in itself a finding about the gene and the disease.
ZIKV infection (continued). "Moreover, an increase in the TNF and IL-6 families of cytokines may have implications on other important testicular cell functions during ZIKV infection, including steroidogenesis and leukocyte transmigration, and therefore further investigation in this area is also warranted." (PMID 29880853, 2018). "We show that the immune response during the acute phase of ZIKV infection is polyfunctional and broadly inflammatory, as evidenced by significantly elevated levels of IL-4, IL-17, IFN-γ, IL-1β, IL-1Ra, TNF-α, and IL-6 in patients as compared to controls." (PMID 29768624, 2018). "Differentially expressed genes (DEGs) and pathway analysis showed that ZIKV infection triggered strong antiviral immunity and inflammation responses, including the interferon (IFN), NF-κB, and tumor necrosis factor (TNF) signaling pathways." (PMID 30228241, 2018). "The pro-IL-1β, TNF-α, IL-8, and MCP-1 mRNAs were induced by LPS, ZIKV genomic RNA, HCV genomic RNA, and ZIKV infection." (PMID 29317641, 2018). "We found that gamma interferon (IFN-γ) and tumor necrosis factor alpha (TNF-α) T cell responses to NS3 differentiated DENV and ZIKV infections with 94% sensitivity and 92% specificity." (PMID 30087165, 2018). "Thus, it is possible that ZIKV infection could activate neuronal production of TNFα and IL-1β." (PMID 28878777, 2017). "Thirty days after ZIKV infection we saw a strong polyfunctional CD4+ T-cell response, where the CD4+ T cells from BS14 made IFN-γ (0.70%), TNF-α (9.6%) and CD107a (2%) in response to the E peptide pool stimulation." (PMID 28643775, 2017). "ZIKV infection, for example, reduces the interaction between F-actin and ZO-1, enhancing BTB permeability, whereas mumps virus infection impairs BTB integrity through TLR2-mediated TNF-α production in SCs." (PMID 41596343, 2026). "This longitudinal follow‐up provides chronological information on the immune response to mild‐to‐moderate ZIKV infection, with an early antiviral response dominated by IFN‐γ, TNF‐α and regulated by IL‐10, followed by a peak of Th1 and then Th17‐associated cytokines that persists for up to 1 month." (PMID 41556482, 2026). "Using a qRT-PCR assay, high expression levels of pro-inflammatory cytokine genes, including IL6, IL15, IFNγ, TNFα, CXCL15, IL18, and IL1β, were confirmed in ZIKV-infected placentas, suggesting that ZIKV infection may trigger placental inflammation." (PMID 41263557, 2025). "During ZIKV infection, MEL reduced TNFα, MX1, and IFI44L levels." (PMID 40821819, 2025). "Similar patterns of mRNA expression were also observed for TNF-α, IL-1β, IL-8 and CXCL-10 (IP-10) cell models following ZIKV infection; however, with a much higher level of IP-10 expression observed in the ZIKV-susceptible HASTR/ci35 cells compared with the ZIKV-resistant CCF-STTG1 cells." (PMID 35053142, 2022). "PTX treatment did not prevent death caused by ZIKV infection in SH-SY5Y cells, as quantified by LIVE/DEAD staining followed by FCM analysis, suggesting that TNF-α synthesis does not seem to be determinant for ZIKV-induced apoptosis in SH-SY5Y cells." (PMID 34834918, 2021). "Our group and others have demonstrated that ZIKV infection in immunocompetent mice can lead to induction of CD8 T cell immunity, featuring the production of key effector cytokines such as IFN-γ or TNF-α, and the cytolytic molecule granzyme B, suggesting they are important for ZIKV immunity." (PMID 34193875, 2021). "ZIKV infection in primary Tupaia cells induced an upregulation of cytokine mRNA levels over the infection time, including those of IL-6, IL-8, TNF-α, IFN-β, CXCL9, and MX1, where IL-6, IL-8, and TNF-α mRNA levels were significantly elevated 6 h post-infection." (PMID 31842286, 2019). "The intercellular cell adhesion molecule (ICAM-1) a cell surface receptor that can be up regulated by IFNγ, IL1β and TNFα in SCs51 showed increased mRNA expression during culture but was not modulated by ZIKV infection." (PMID 31289325, 2019).
ZIKV infection (continued). "Furthermore, we found strong correlations between TNF-a and CCL5 concentrations and the percentages of circulating neutrophils and lymphocytes in acute ZIKV infection." (PMID 29768624, 2018). "However, DENV/ZIKV coinfection decreased the ability of CD4+ T cells to produce IFNγ+, TNF+, TNF+ IFNγ+, and TNF+ IL2+, compared to DENV and ZIKV infections." (PMID 29282904, 2018). "Of note, significantly increased IFN-γ and TNF-α levels were absent in ZF in contrast to DF, pointing toward a Th2 bias in ZIKV infections." (PMID 26702627, 2016). "Furthermore, ZIKV infection reduced the levels of CASP1-p20 in both iBMDMs and BMDMs treated with LPS plus Ni, as well as the levels of CASP3-p17 and CASP7-p20 in both cell types treated with TNF plus CHX." (PMID 39976465, 2025). "Additionally, we found that ZIKV infection does not significantly reduce the levels of phosphorylated MLKL (p-MLKL) induced by z-VAD-fmk combined with TNF plus SM164 (TSZ), indicating that ZIKV infection does not inhibit necroptosis." (PMID 39976465, 2025). "ZIKV infection similarly did not affect the expression level of IL-12p70 and TNF-α." (PMID 39095588, 2024). "Here, we found that TNF transcript levels were upregulated after ZIKV infection, although we did not detect significant intracellular and soluble levels of TNF-α protein, and treatment with TNF-α synthesis inhibitor PTX did not affect ZIKV apoptosis in SH-SY5Y cells." (PMID 34834918, 2021). "ZIKV infection induced a clear antiviral immune response in these cells as shown by the production of high levels of IFN-α, IFN-β and IFN-γ, as well as neurotoxic factors such as TNF-α, IL-1β and IL-6 during the first hours of infection with maximum levels at 48 hpi." (PMID 30359409, 2018). "The Th1 cells induced by ZIKV infection also exhibited a high degree of poly-functionality (multiple cytokine production), as over 65% of responding CD11a+CD49d+ CD4+ T cells were IFN-γ+TNF-α+ double-producers, and over 60% were IFN-γ+TNF-α+IL-2+ triple-producers." (PMID 28231312, 2017). "ZIKV infection induced increased SC expression of IL-6, interferon (IFN)β1, IFN-λ, IFIT-1, TNFα and IL-23A mRNAs as well as IFN-λ receptors and negative regulators of IFN signaling." (PMID 31289325, 2019).
nephritis (78 papers, 1995 to 2026). Inflammation of renal tissue. "Interleukin-1 and tumor necrosis factor are the famous inflammatory cytokine related to nephritis caused by autoimmune lupus and ischemia-reperfusion injury." (PMID 24734070, 2014). "Our finding that CCL3 inhibition enhances pathology is similar to the finding that in a model of nephritis CCR1−/− (the main receptor for CCL3) mice have enhanced pathology associated with increased TNF levels." (PMID 20195359, 2010). "It has been reported that low levels of TNF-α may promote SLE in predisposed mice and that the treatment of (NZB/NZW) F1 mice with TNF-α ameliorates nephritis, and low TNF-α expression may be implicated also in human SLE patients." (PMID 22192852, 2011). "Taken together our results confirm that TNF-α plays an important role in the induction and development of HgCl2-induced nephritis and highlights the pathogenic importance of the local release of TNF in those renal diseases in which prominent glomerular macrophage accumulation is a constant feature." (PMID 18475678, 1995). "The mRNA expressions of TNF-α and IL-1β increased significantly, which continuously activated the NF-κB signaling pathway, potentially leading to kidney inflammation." (PMID 40451077, 2025). "Our results show that DASA treatment led to the upregulation of pro-inflammatory cytokines, such as NF-κB, TNF-α, and IL-6 suggesting the development of kidney inflammation." (PMID 39744177, 2025). "During the development of kidney inflammation, TNF-α can activate the NF-кB pathway, enhance the expression of COX2 and other inflammatory genes, induce the production of more inflammatory mediators, and further amplify the inflammatory response." (PMID 40916492, 2025). "IL-9 produced by a subset of CD4+ T helper cells promotes mast cell infiltration and degranulation in AIN, triggering TNF-α release and kidney inflammation, as evidenced by increased TNF-α-positive cells and mast cells in AIN biopsies." (PMID 41515589, 2025). "Another study found that miR-128-3p increased the expression of inflammatory cytokines such as TNF-α, IL-1β, and IL-6, whereas IL-1β is a key cytokine in kidney inflammation." (PMID 41440335, 2025). "Taken together, our results suggest that the TMAO can enhance TNF-α mediated kidney inflammation by inducing the release of several cytokines, chemokines, inflammatory-and growth mediators from renal fibroblasts." (PMID 38643262, 2024). "It has also been reported to suppress macrophages infiltration in murine nephritis model and to interfere with NFκB signaling and hence preventing inflammation, in addition to reducing the levels of circulating TNF-α and other inflammatory mediators." (PMID 38910880, 2024). "Another study in an inflammatory rat model showed that elevated TNF and interleukin-1 (IL-1) levels increased the severity of glomerular damage in nephritis." (PMID 39600722, 2024). "There has also been increasing evidence regarding the use of TNF blockade in other irAEs such as pneumonitis and nephritis." (PMID 37958355, 2023). "The results showed that the AGE-RAGE, IL-17 and TNF signal pathways were the important pathways of SHP acting on nephritis." (PMID 37361210, 2023). "Tomosugi’s study showed that the pretreatment of rats with TNF and IL-1 increased the severity of glomerular injury in nephritis." (PMID 37710270, 2023). "The newly identified action of miR-505 in augmenting the level of proinflammatory mediators such as TNF-α in PBMCs corroborates vascular inflammation and kidney inflammation as a result of agomir-505 in vivo administration." (PMID 35571179, 2022). "GM can increase the inflammatory infiltration of macrophages and produce TNF-α, IL-6, and other inflammatory factors, which promote the development of kidney inflammation." (PMID 36296715, 2022). "General proinflammatory and inflammatory cytokines are increased in IgA vasculitis and nephritis, such as IL-1β, IL-4, IL-6, IL-8, IL-12p70, IL-17A, TNF-α, and IFN-γ." (PMID 34299162, 2021).
nephritis (continued). "The correlation analysis between nephritis and different concentrations of cytokines showed that the levels of IL-6 (r = 0.368, P = 0.035) and TNF-α (r = 0.415, P = 0.031) were positively correlated with the occurrence of nephritis." (PMID 33882880, 2021). "Along with the results of network pharmacology analysis, chemokines and cytokines, in particular TNF-α, have been reported to be critical for inflammatory responses and subsequent tissue injury in nephritis." (PMID 32765640, 2020). "Pooled lysates demonstrated an increase of TNFα protein amount in nephritis rats compared with the control group." (PMID 33070237, 2020). "It has been shown that proinflammatory cytokines Interleukin-1 Beta (IL-1β) and tumor necrosis factor-α (TNF-α) contribute to the progression of nephritis in animal models and patients." (PMID 29643988, 2018). "Rat Thy-1N was reproduced and then the mRNA and/or protein levels of C5a, IL-6 and TNF-α in the rat renal tissues were detected at different time points after the nephritis induction." (PMID 27583546, 2016). "These combined properties of eugenol can be used to explain the observed reduction in TNF-α expression, as well as the reduction of kidney inflammation." (PMID 26884642, 2016). "Further diseases linked to PPROM were nephritis or glomerulonephritis (ACE, COL4A3, COL4A4, IGF1, NOS2, REN, TNF)." (PMID 25264875, 2014). "Ad-IFNα treatment in NZB/W F1 mice results in elevated renal expression and increased serum levels of TNFα concomitant with the onset of nephritis, making these mice an ideal model to study the efficacy of TNF receptor 2 (TNFR2)-Ig." (PMID 24106491, 2013). "In our model of mercury-induced nephritis, the levels of TNF-α and IL1-β cytokines as well as the expression of VCAM-1 molecule were significantly increased at day 13 of the disease in comparison with the controls." (PMID 17250768, 2007). "IL-1β, either directly or through the induction of other cytokines such as IL-6 and TNF-α, promotes the development of kidney inflammation by increasing the expression of adhesion molecules and chemotactic factors and by recruiting inflammatory cells, thereby inducing kidney injury." (PMID 39117988, 2025). "Furthermore, data from earlier studies indicated that therapy with WS significantly inhibited nephritis, proteinuria, TNF-α, IL-6, and ROS." (PMID 39502378, 2024). "Therefore, in this study, an in vitro nephritis model was established using rat MCs, which were then subjected to TNF-α stimulation." (PMID 35624699, 2022). "Along with increased renal expression of Il1b, TNF-α, Vcam1 and E-selectin, increased lymphatic vessel density and enhanced expression of Lyve-1 in the kidney further confirm that elevated level of circulating miR-505 leads to kidney inflammation in vivo." (PMID 35571179, 2022). "Moreover, increased histone methylation H3K4me3 of TNF has been found to be related to kidney inflammation." (PMID 35633893, 2022). "In addition, IL-17 is upregulated in IgA vasculitis and nephritis; however, IL-17 inhibitors are also related to the occurrence of IgA vasculitis, suggesting that TNF and IL-17 are involved in the cytokine production mediated by IgA vasculitis." (PMID 34299162, 2021). "A high dose of SSC might disrupt the balance of GR- or TNF-α- regulated systems, and counteract the anti-inflammatory benefits in nephritis." (PMID 33104740, 2020). "Antroquinonol, one of the main bioactive ubiquinone derivatives in A. camphorata, exhibited anti-inflammatory effects in lipopolysaccharide-stimulated RAW 267.4 cells and reduced the production of tumor necrosis factor (TNF)-α and interleukin (IL)-1β in mice with nephritis." (PMID 30336562, 2018). "In NZBWF1 mice, TNF-α plays a potentially protective role during the early stage of lupus nephritis since treatment with recombinant TNF-α appeared to delay the development of nephritis." (PMID 26441980, 2015).
nephritis (continued). "In a study of 60 consecutive childhood-onset SLE patients, serum IL-12 and TNF-α levels were significantly increased in patients with nephritis when compared to first-degree relatives and healthy controls, and TNF-α levels were significantly increased in patients with active disease." (PMID 24692841, 2014). "In addition, other clinical research has shown that TNF-alpha is closely related to severe nephritis during human leptospirosis." (PMID 24130911, 2013). "In the context of GN these data suggest that glomerular activation of TNFR2 by membrane-bound TNF may trigger local cell injury which is essential for the induction of nephritis, as shown in the NTN model in vivo." (PMID 23869211, 2013). "Young pre-autoimmune mice that were treated with IFNα quickly developed renal immune complex deposition and nephritis, accompanied by increased serum levels of pro-inflammatory cytokines such as TNFα and IL-6, activation of DCs, B cells, and T cells, as well as an enhanced germinal center response." (PMID 24106491, 2013). "Furthermore, replacement therapy with recombinant TNF-alpha induces a significant delay in the development of the nephritis." (PMID 27713252, 2010). "In addition, whole isolated glomeruli from HgCl2-induced nephritis secreted TNF-α commencing on day 8, being maximally detected on day 11 and preceding, between 2 to 3 days, the development of proteinuria." (PMID 18475678, 1995). "Notably, TNF deficiency is not sufficient to prevent tissue damage and mortality due to nephritis in genetically predisposed models." (PMID 35104241, 2022). "In addition, TNF-α is also involved in downregulating the immune response in NTS nephritis, the TNF-α knock out T cell may cause more severe nephritis." (PMID 33104740, 2020). "The protein interaction analysis network showed that TNF, VEGFA, PTGS2, MMP9, MAPK1, and other proteins were the key targets of the 7 phenolic acids in the treatment of nephritis." (PMID 36998608, 2023). "Pathway analysis revealed that the targets of nephritis were mainly enriched in the AGE-RAGE, hypoxia-inducible factor-1, interleukin-17, and tumor necrosis factor signaling pathways among others." (PMID 36998608, 2023). "The key targets such as TNF, VEGFA, PTGS2, MMP9, and MAPK1 are directly or indirectly related to the 7 phenolic acids and multiple nephritis-related pathways." (PMID 36998608, 2023). "After identifying the main targets (TNF, AKT1 and PTGS2) of SHP in nephritis treatment, we further conducted a KEGG analysis to reveal the signal pathways of these main targets." (PMID 37361210, 2023). "The results showed that TNF, AKT1 and PTGS2 were the main targets of SHP in treating nephritis, which was consistent with previous reports." (PMID 37361210, 2023). "Nephritis targets are mainly enriched in the AGE-RAGE, HIF-1, IL-17, and TNF signaling pathways during diabetic complications." (PMID 36998608, 2023). "SIRT1 overexpression significantly suppressed F4/80, and SRT1720 treatment reduced MCP-1, TNFα, and F4/80 in the offspring exposed to maternal HFD, suggesting the anti-inflammatory effects of SIRT1 against maternal obesity-induced kidney inflammation." (PMID 30641941, 2019). "A review of the literature showed that TNF blockade is effective in SLE patients with arthritis, nephritis and skin disease." (PMID 27713252, 2010). "We did not observe a similar increase in serum TNF‐α levels in our nephritis group (n = 5), though our small sample size limits the generalizability of these findings." (PMID 40590520, 2025). "In a study by Tae‐Sun Ha, patients diagnosed with IgAV nephritis were compared with patients without nephritis, and it was found that serum and urinary TNF‐α levels were significantly higher in patients with IgAV nephritis." (PMID 40590520, 2025).